CCL5 (C-C motif chemokine ligand 5)
Diseases named in the same sentence as CCL5 in open-access papers (continued):
Sharing a sentence is not in itself a finding about the gene and the disease.
gingivitis (5 papers, 2018 to 2026). A disorder involving inflammation of the gums; may affect surrounding and supporting structures of the teeth. "A significant dose-dependent increase in the secretion ofcytokines IL-6, CXCL8, CCL2, and CCL5 was found for gingiva equivalents exposedto commensal, gingivitis, and cariogenic microbiome." (PMID 28892653, 2018). "The expression of CCL5 in the gingival crevicular fluid of patients with gingivitis may depend on the patient’s body mass index." (PMID 38139161, 2023). "Lean individuals with gingivitis had higher CCL5 levels than lean individuals with healthy gums." (PMID 38139161, 2023). "Furthermore, we found that gingivitis biofilm in particular could activate CCL5 (MyD88-dependent and independent) transcription and cariogenic biofilm could activate CXCL10 (MyD88-independent) transcription." (PMID 31448244, 2019).
Impaired glucose tolerance (5 papers, 2009 to 2025). An abnormal resistance to glucose, i.e., a reduction in the ability to maintain glucose levels in the blood stream within normal limits following oral or intravenous administration of glucose. "CCL5, also known as RANTES, has been associated with T2DM and impaired glucose tolerance." (PMID 39275140, 2024). "CCL5 (RANTES) was also found at higher levels in the circulation of 236 patients with T2DM, 242 individuals with impaired glucose tolerance (IGT) but not in 244 individuals with normal glycemic control." (PMID 33692997, 2021).
mesothelioma (5 papers, 2012 to 2025). A usually malignant and aggressive neoplasm of the mesothelium which is often associated with exposure to asbestos. "Significantly higher levels of multiple chemokines were expressed in R- vs NR- mesotheliomas, namely CCL5, CCL16, CCL17, CCL19, CCL21, CCL25, and CXCL14 Benajmini-Hochberg adjusted P values < 0.05." (PMID 40691143, 2025). "CCL5 is also substantially elevated in the peripheral blood of patients with mesothelioma compared to asbestos workers and healthy individuals and the CCR5 receptor is present on T-cells in pleural effusions." (PMID 31867277, 2019). "Chemokine signals that attract monocytes in mesothelioma include CCL2, CCL4, CCL5, and CXCL12 and these appear to be of mesothelioma cell origin." (PMID 31867277, 2019). "An antibody-based cytokine array system using supernatant of mesothelioma cell lines and the corresponding patient's pleural effusions found that high levels of RANTES/CCL5 proteins were secreted by mesothelioma cells." (PMID 22737246, 2012). "Moreover, ERK5 ablation in malignant mesothelioma cells is accompanied by a significant reduction in tumor size as a result of the downregulation of critical angiogenesis-related (IL-8, VEGF) and proinflammatory (RANTES/CCL5, MCP-1/CCL2) cytokines." (PMID 35053510, 2022). "We show in this work that MMP2, BAFF/BLyS/TNFSF13B, RANTES/CCL5 and TNFAIP6/TSG-6 are highly expressed in 3D mesothelioma but not in monolayers." (PMID 22737246, 2012).
metastatic cancer (5 papers, 2015 to 2023). A carcinoma which has spread from the original site of growth to another anatomic site. "Our study demonstrates that host responses against metastatic cancer are mainly regulated by homeostatic Ccl5 expression in local tissue-resident immune cells." (PMID 32218434, 2020). "Compared with primary cancer tissues, the expression of both CCL5 and its receptors was two-fold higher in the metastatic cancer tissues (p<0.0001)." (PMID 25788271, 2015). "Interestingly, the homeostatic CCL5 expression from the host’s immune cells has significant impacts on priming functional states of the immune cells at nonimmune tissues, such as lungs, resulting in altered tumor immunity against metastatic cancer." (PMID 32218434, 2020). "This analysis showed that both mRNA and protein levels of CXCL10, CCl5 and IRF7 protein levels were elevated in metastatic cancer cells in culture and reduced in 66cl4-derived primary tumors." (PMID 36882786, 2023).
neuropathy (5 papers, 2017 to 2023). A disorder affecting the nervous system that manifests with pain, tingling, numbness, and/or muscle weakness. "They both activate glial and immune cells to release proinflammatory cytokines such as TNF-α, IL-1β, IFN-γ, and IL-6, and chemokines such CCL2 and CCL5, which cause neuronal hyperexcitability, neurodegeneration, neuropathies including neuropathic pain." (PMID 35095888, 2021). "A blockade of the CCL3-CCL4-CCL5/CCR5 axis with maraviroc, a CCR5 antagonist, also reduces NP symptoms by inhibiting the expression of CCL3, CCL4 and CCL5 and intensifies morphine and buprenorphine analgesia in the CCI neuropathy model." (PMID 35330149, 2022). "Furthermore, the serum cytokine profiles of CTS patients were readily distinguishable from those of controls with distinct patterns of the chemokines CCL2, CCL4, CCL5, CXCL8 and CXCL10 and the growth factors VEGF, PDGF and G-CSF, which may be induced by the neuropathy." (PMID 28811623, 2017). "In our study, we have shown that the levels of two highly pronociceptive chemokines that change in neuropathy, CCL2 and CCL5, did not increase in animals repeatedly receiving mirogabalin." (PMID 37513935, 2023).
periodontal disease (5 papers, 2010 to 2023). "For example, vitamin D deficiency is associated with an increased risk of periodontal disease, which is partly related to an increased proinflammatory response, including the production of CCL5 in the gingiva." (PMID 38139161, 2023). "Some studies have shown that CCL5 levels in GCF depend on the severity of periodontal disease." (PMID 38139161, 2023). "In the course of periodontal disease, various proinflammatory mediators occur, such as interleukin- (IL-) 1, IL-6, and IL-8, IFN- γ, CCL5, TNF-α, prostaglandins, and metalloproteinases." (PMID 31355282, 2019).
peritonitis (5 papers, 2012 to 2020). Inflammation of the peritoneum (tissue that lines the abdominal wall and covers most of the organs in the abdomen). "In contrast to previously published results for CCL5 mediated peritonitis, heparin showed a small tendency to enhance recruitment in this model." (PMID 23087686, 2012). "HPFB-derived CCL5 may thus contribute to the intraperitoneal recruitment of mononuclear leukocytes during peritonitis." (PMID 24523572, 2014).
respiratory syncytial virus infection (5 papers, 2014 to 2025). "In response to RSV (respiratory syncytial virus) infection, CCL5 may exacerbate inflammation and airway hyperreactivity, but deletion of CCL5 in response to influenza virus infection leads to decreased survival in mice." (PMID 26965109, 2016). "EVs produced during respiratory syncytial virus infection deliver viral components to stimulate monocytes and airway epithelial cells to produce chemokines such as MCP-1/IP-10/CCL5 and CCL5/IP-10/TNF-α, respectively, for counteracting infection." (PMID 41050925, 2025). "Considering that adenovirus and respiratory syncytial virus infection in KU812 cells fails to induce CCL5 secretion, we postulate that CCL5 might be a selectively induced chemokine in mast cell/basophil-Flavivirus infections." (PMID 35862953, 2022).
RSV bronchiolitis (5 papers, 2014 to 2024). "In a previous longitudinal study within the same cohort as in the current study, we found that baseline TNFα and CCL5 gene expressions were associated with the clinical course of RSV bronchiolitis, as evaluated with the WDS and BROSJDD scores." (PMID 39403383, 2024).
synovitis (5 papers, 2016 to 2025). Inflammation of a synovial membrane. "Whereas CCL2 and CCL3 returned to baseline levels within 24 h, CCL5 and CCL11 remained elevated from baseline for 72 h in the synovitis model." (PMID 33980227, 2021). "Following synovitis, CCL5 concentrations were increased from baseline at 6, 12, and 72 h and were greater in the synovitis joint as compared to the contralateral MCJ at 6, 72, and 168 h (synovitis CCL5 baseline: 167 ± 160 pg/mL; synovitis CCL5 peak: 634 ± 159 pg/mL, p = 0.0001)." (PMID 33980227, 2021).
thyroid cancer (5 papers, 2020 to 2025). "Our study revealed that with decreased expression in thyroid cancer tissues, CCL5 may be associated with immune escape." (PMID 40299520, 2025). "We used LASSO Cox regression to construct a model for the evaluation of thyroid cancer prognosis, and a risk model consisting of six genes (ACSL5, HSD17B11, CCL5, NCF2, PSME1, and ACTB) was subsequently developed." (PMID 40299520, 2025). "Conversely, one previous study reported significantly lower levels of CCL5/RANTES in 23 thyroid cancer patients (18 patients with PTC) compared to 23 healthy participants, while our study included more participants (63 patients with PTC and 63 healthy participants)." (PMID 40150133, 2025). "CCL2 is overexpressed in liver, breast, gastric, and thyroid cancer 11; CCL5 is overexpressed in gastric, pancreatic, breast, colorectal, prostate, liver, and thyroid cancer 12; CCL7 is markedly upregulated in lung, gastric, colorectal, and uroepithelial cancer." (PMID 33123272, 2020). "Further validation using qRT–PCR in 100 paired thyroid cancer and adjacent normal tissues revealed consistent upregulation of ACSL5 and NCF2 in tumour tissues and downregulation of HSD17B11, CCL5, and ACTB." (PMID 40299520, 2025). "Several researchers have additionally demonstrated that four chemokines, CXCL1, CCL5, CCL20 and CCL21, biologically affect thyroid cancer cells by modulating inflammation and the immune microenvironment." (PMID 33345267, 2021).
acute GVHD (4 papers, 2013 to 2024). "Similarly, elevated levels of CCL2, CCL3, and CCL5 in the liver and intestines of acute GVHD mice mediate the infiltration of neutrophils and activated T cells." (PMID 39840040, 2024). "In a murine model of acute GVHD, blockade of PI3Kγ resulted in a reduction in the expression of pro-inflammatory chemokines, namely CCL3 and CCL5." (PMID 39840040, 2024).
adenoma (4 papers, 2011 to 2025). A neoplasm arising from the epithelium. "We found that the tumor-derived cytokine CCL5 is upregulated in AIP-mutation-positive human adenomas." (PMID 30867568, 2019). "We identified that tumor-derived cytokine CCL5 is upregulated in AIP-mutation-positive human adenomas." (PMID 30867568, 2019). "CCL19, CCL21, CCL23, CCL5, were found to have reduced expression in the adenoma and adenocarcinoma compared to normal mucosa." (PMID 21249124, 2011). "Similarly, CCL5 was significantly downregulated in adenocarcinomas (p = 0.035), although this difference was not statistically significant in the paired analysis (53% of adenomas had higher CCL5 expression, p = 0.082)." (PMID 40699620, 2025).
autoimmune uveitis (4 papers, 2011 to 2025). An autoimmune form of uveitis (disease). "Increased expression of CCL5 has been associated with autoimmune uveitis and has been shown to be a potential serum marker of diabetic retinopathy." (PMID 21527995, 2011). "H23K-RANTES showed attenuation of autoimmune uveitis in rats based on displacement of wild type CCL5 from its proteoglycan-co-receptor." (PMID 22807925, 2012).
childhood asthma (4 papers, 2012 to 2021). "A meta-analysis published in 2020 revealed that RANTES(CCL5) -403G/A and -28C/G genetic polymorphisms significantly contribute to the development of childhood asthma." (PMID 34516405, 2021).
Chlamydia infection (4 papers, 2008 to 2023). "In this study, Chlamydia infection enhanced IgG2a Ab responses, which were reduced after CCL5 inhibition." (PMID 18700040, 2008). "The present study shows that 7 days after genital Chlamydia infection, CCL5, CCR5, and IFNγ mRNA levels were elevated in inductive sites, while CCR5 mRNA expression was higher in the fallopian tubes than in the uterus and cervix." (PMID 18700040, 2008). "Following Chlamydia infection, mast cell-deficient mice displayed attenuated CXCL2 production, with the levels of other proinflammatory mediators including CCL2, CCL5, CXCL13, and effector mediators assessed as not being significantly altered." (PMID 37138882, 2023).
chronic hepatitis B (4 papers, 2014 to 2026). "The serum level of CCL5 is a reliable marker that can predict disease progression in chronic hepatitis B patients." (PMID 31996147, 2020). "To further evaluate the role of CXCR3 and CCL5 in the course of chronic hepatitis B and their potential for future treatment, we analyzed single-cell RNA sequencing data from the public database GSE247322, examining the expression of CXCR3 and CCL5 in PBMCs of CHB patients with high viral load." (PMID 41258710, 2026).
chronic obstructive pulmonary disease (4 papers, 2012 to 2021). A chronic and progressive lung disorder characterized by the loss of elasticity of the bronchial tree and the air sacs, destruction of the air sacs wall, thickening of the bronchial wall, and mucous accumulation in the bronchial tree. "Indeed, LXR activation by GW3965 has shown anti-inflammatory effects (reduction of CXCl10 and CCL5 levels) in lung macrophages from chronic obstructive pulmonary disease patients." (PMID 27149934, 2016). "In bronchial mucosa of patients with chronic obstructive pulmonary disease (COPD), CCL5, and to a lesser extent CXCL7, have been found to be the most abundant chemokine expressed in the bronchial epithelium and are associated with an increase of neutrophil activation." (PMID 22807925, 2012).
chronic viral hepatitis (4 papers, 2021 to 2025). "In the progression of chronic viral hepatitis, CCL5 and CXCL10 modulate the cytopathic and antiviral immune responses of natural killer cells and T lymphocytes." (PMID 40070835, 2025). "Moreover, during the development of chronic viral hepatitis and MASH, CCL2 and CCL5 played an important role." (PMID 39605886, 2024). "However, the effect of CCL5 on chronic liver disease progression and HCC development was reported to be more significant in steatohepatitis than in viral hepatitis." (PMID 34041839, 2021).
coronary atherosclerosis (4 papers, 2011 to 2021). Atherosclerosis of the coronary vasculature. "Thus, the instability of CCL5 levels became its unreliable maker of coronary atherosclerosis." (PMID 26688689, 2015).
delirium (4 papers, 2022 to 2025). A disorder characterized by confusion; inattentiveness; disorientation; illusions; hallucinations; agitation; and in some instances autonomic nervous system overactivity. "LM‐ and AS‐induced delirium led to microglial activation in the hippocampus as evidenced by up‐regulation of microglial activation‐related genes (such as Il6ra, Tyrobp, Cd68, Aif1, Csf1r, and Trem2) and of relevant inflammatory factors (such as Il‐1β, Tnfα, Ccl2, Ccl5, and Ccl8)." (PMID 35713240, 2022). "However, there are no data whether delirium is associated with M1 macrophage, Th1, Th2, Th17, Treg or CIRS cytokine profiles, and whether a neurotoxic cytokine profile including M1, Th1, Th17 and neurotoxic chemokines, such as CCL11, CCL2, CCL3, CCL5, and CXCL10) is associated with delirium." (PMID 35641947, 2022).
disc degeneration (4 papers, 2020 to 2024). "The alterations of several cytokines in peripheral blood of patients with degenerative disc diseases are consistent with those found in intervertebral discs, such as interleukin-6 and CCL5." (PMID 32487144, 2020).
fungal infections (4 papers, 2018 to 2024). "Alternatively, NK cells may simply empty their granules upon A. fumigatus recognition, but further focus on the expression of cytokines other than CCL5/RANTES for acute treatment of the fungal infection." (PMID 30563459, 2018).
glaucoma (4 papers, 2015 to 2025). Increased pressure in the eyeball due to obstruction of the outflow of aqueous humor. "CCL5 is a pro-inflammatory cytokine whose elevation has been linked to retinal stress associated with glaucoma and age-related macular degeneration." (PMID 32765507, 2020). "Here we examined expression of the β-chemokine CCL5 and its receptors in the mouse retina and evaluated its relevance in glaucoma, a common optic neuropathy associated with sensitivity to intraocular pressure (IOP)." (PMID 28936366, 2017). "Here, we sought to characterize expression of CCL5 and its high-affinity GPCRs in murine retina and discern the potential relevance of CCL5 signaling to glaucoma." (PMID 28936366, 2017). "Here we examined the potential relevance of the β-chemokine CCL5 in glaucoma." (PMID 28936366, 2017). "In addition to changes in overall expression, it is likely that the functional consequences of aging- and glaucoma-related CCL5 signaling differ from that of constitutive signaling." (PMID 28936366, 2017). "Using a variety of molecular and histological techniques, we found that CCL5 and its high-affinity receptors are constitutively expressed in the murine retina and are differentially induced by both aging- and IOP-related stressors associated with glaucoma." (PMID 28936366, 2017). "To determine whether glaucoma-related stressors alter expression of CCL5 signaling machinery, we examined protein expression and localization of CCL5, CCR5 and CCR3 in retina from age-matched C57Bl/6and DBA/2 mice." (PMID 28936366, 2017). "The protective effect of RANTES on glaucoma in this study suggests that it may serve as a biomarker for early diagnosis and provide a basis for the development of neuroprotective therapies targeting the CCL5 pathway." (PMID 40687727, 2025). "To determine whether CCL5, like the β-chemokine Ccl2, is involved in retinal neurodegeneration and specifically in glaucomatous degeneration of RGCs, we examined CCL5 expression and localization in the DBA/2 model of glaucoma." (PMID 28936366, 2017).
head and neck cancer (4 papers, 2018 to 2025). A primary or metastatic malignant neoplasm affecting the head and neck. "In this study, we analyzed the immune regulatory properties of EGFR signaling in head and neck cancer cells and showed that it suppresses type 1 cytokine-induced expression of CCL2, CCL5, CXCL9, CXCL10 and IL-6 while promoting the expression of IL-1β." (PMID 30192802, 2018).
hepatitis B (4 papers, 2016 to 2025). "Because CCR5, a major chemokine receptor for CCL3 and CCL5, is known to be critical in hepatitis B, Ku70/80 sensing of HBV DNA likely plays a critical role in immune cell recruitment in response to HBV infection." (PMID 27994596, 2016). "CCL5 and CCL3 are well characterized as inflammation-associated chemokines, and their main receptor, CCR5, is also essential in hepatitis B progression." (PMID 27994596, 2016).
Huntington disease (4 papers, 2016 to 2025). Huntington disease (HD) is a rare neurodegenerative disorder of the central nervous system characterized by unwanted choreatic movements, behavioral and psychiatric disturbances and dementia. "In mouse models of prodromal Huntington’s Disease and tauopathies such as Alzheimer’s, CCL5 expression is increased and inhibits autophagy that normally degrades aggregating proteins." (PMID 39175524, 2024). "CCL5 treatment also influences development-related signaling, such as CNTF, VEGF, GNRH, and Huntington’s disease-related signaling molecules." (PMID 39285280, 2024). "Interestingly, CCL5 treatment also enhanced neuron development-related signaling, such as CNTF, VEGF, Huntington’s disease, and Reelin." (PMID 39285280, 2024).
inflammatory skin disease (4 papers, 2015 to 2023). Inflammatory skin disorders covers a broad category that includes many conditions ranging in severity, from mild itching to grave medical health complications These disorders are common in people of all ages and races. "Therefore, the downregulation of RANTES/CCL5, TARC/CCL17, and MDC/CCL22 in keratinocytes may be a potential target for treating inflammatory skin diseases." (PMID 30642008, 2019).